IGHD6-6 (immunoglobulin heavy diversity 6-6)
Synonyms: IGHD66; D(N4)
Gene: Immunoglobulin diversity (D) gene on chromosome 14 (105,910,410 to 105,910,427, reverse strand). Ensembl gene ENSG00000228131.
Diseases named in the same sentence as IGHD6-6 in open-access papers:
IGHD6-6 is named in the same sentence as 1 disease in open-access papers, as found by Europe PMC text mining. Sharing a sentence is not in itself a finding about the gene and the disease.
IGHD6-6 shares sentences with these, for which no sentence is quoted: pneumoniae (1 paper).